ALB (albumin)
Diseases named in the same sentence as ALB in open-access papers (continued):
Sharing a sentence is not in itself a finding about the gene and the disease.
cancer (continued). "The derived in vivo doses based on the albumin adducts can then further be applied in different procedures to aid in quantitative cancer risk estimation of PAHs." (PMID 27805056, 2016). "In another previous study symptomatic spinal metastases, pretreatment albumin level, primary cancer site, KPS, and number of visceral metastases were associated with survival." (PMID 27456003, 2016). "Both decreased albumin and increased globulin have been reported to be associated with severity and poor outcome for several types of cancer." (PMID 26966671, 2016). "Decreased preoperative albumin is associated with reduced survival and poor prognosis in other cancer patients." (PMID 26885692, 2016). "Blood biomarkers, such as neutrophil count, monocyte count, platelet count, serum C-reactive protein level, serum albumin level, and interleukin-6 level, for the systemic inflammatory response are associated with cancer prognosis." (PMID 27732629, 2016). "First, lymphocytes and serum albumin are significantly associated with prognosis of cancer patients." (PMID 27344182, 2016). "Both decreased albumin levels and increased globulin levels have been associated with up-regulated inflammation and poor outcome for several types of cancer." (PMID 26966671, 2016). "Low albumin and lymphocytes were independently associated with an increase in cancer specific mortality (all p<0.001)." (PMID 25730322, 2015). "The results of the multivariate analysis of the association between the CONUT score and the albumin level with relapse-free survival and cancer-specific survival." (PMID 26147805, 2015). "As C-reactive protein, albumin and neutrophils were consistently predictive of all-cause, cancer, cardiovascular and cerebrovascular specific mortality, these were taken forward to examine the prognostic value of their combination." (PMID 25730322, 2015). "Growing numbers of studies have demonstrated associations between a low serum albumin level and an increased severity of disease, a high risk of disease progression and poor survival in cancer patients." (PMID 26585371, 2015). "Low albumin and lymphocyte counts were independently associated with an increase in cancer mortality (all p<0.001)." (PMID 25730322, 2015). "A simple inflammation-based scoring system, combining C-reactive protein and serum albumin, is associated with prognosis in patients undergoing cancer treatments." (PMID 26072055, 2015). "Gupta and colleagues examined the association between pre-treatment serum albumin levels and survival of patients with different types of cancer." (PMID 26356222, 2015). "The incorporation of CRP and albumin levels allow to take into account the effects of systemic inflammation and the progressive nutritional decline associated with advanced cancer." (PMID 26496339, 2015). "Recently, an association between elevated albumin-to-creatinine ratio and cancer was reported in a longitudinal population-based study of older individuals." (PMID 24427312, 2014). "The nutritional status of a cancer patient, which can be assessed by the serum albumin level, is known to be associated with survival." (PMID 25298213, 2014). "When dichotomized, only low albumin (odds ratio, 2.6, CI [1.3–5.2]) and high alkaline phosphatase (odds ratio, 2.3, CI [1.7–4.7]) were associated with cancer." (PMID 24762986, 2014). "Multivariate analysis showed that albumin, erythrocyte sedimentation rate, iron, white blood cell count, and lactate dehydrogenase levels were associated with cancer." (PMID 24762986, 2014). "Analysing all factors in stepwise Cox regression revealed that age, BMI, albumin, calcium, eGFR, 25D, prevalent cancer and prevalent CVD were independently associated with all-cause mortality." (PMID 23587028, 2013). "We previously identified albumin-associated lipid- and, more specifically, saturated fatty acid-induced transdifferentiation programs in human cancer cells (HCCLs)." (PMID 23961369, 2012).
cancer (continued). "Further predictors of all-cause mortality were male sex, low body mass index and cancer, while cardiovascular mortality increased with urinary albumin concentration." (PMID 20698977, 2010). "On multivariate analysis, these associations with the presence of cancer persisted in age, deprivation, C-reactive protein, albumin, adjusted calcium, Alk phos and GGT (all P<0.01)." (PMID 20717110, 2010). "On multivariate analysis, the associations with the presence of cancer remained with age, deprivation, C-reactive protein, albumin, adjusted calcium, Alk phos and GGT (all P<0.01)." (PMID 20717110, 2010). "In the non-cancer cohort the strongest associations (Spearman's correlation ⩾0.3) were between C-reactive protein and albumin, C-reactive protein and Alk phos, AST and ALT, AST and GGT and ALT and GGT." (PMID 20717110, 2010). "Ecological and observational studies suggest that low serum albumin is associated with higher mortality from cancer." (PMID 21176210, 2010). "This review summarizes all available epidemiological literature on the association between pretreatment serum albumin levels and survival in different types of cancer." (PMID 21176210, 2010). "BMI and serum albumin were significantly lower in the cancer patients with weight loss than in both other groups." (PMID 11875702, 2002). "Preoperative serum albumin may serve as a valuable marker of physiological reserve and perioperative risk stratification in geriatric cancer patients." (PMID 41840567, 2026). "Importantly, albumin concentrations differ between women and men, and sex-differences have been identified with regard to the association between plasma albumin and cancer-related symptoms." (PMID 41504962, 2026). "Although covalent conjugation of siRNA to albumin has been explored to some extent, lipid–siRNA conjugates that enable reversible in situ association with native circulating albumin has been proof-of-concept tested mostly in cancer studies." (PMID 40379798, 2025). "Low levels of albumin have been associated with the poor survival of cancer patients." (PMID 40095884, 2025). "Low albumin levels may not only indicate deteriorating liver function but also increase the risk of cancer invasion and metastasis." (PMID 41008815, 2025). "PNI, calculated from serum albumin levels and lymphocyte counts, is a well-established indicator for assessing nutritional and immune status and predicting risk in malignant tumors, which has been extensively used to evaluate various solid tumors’ treatment outcomes." (PMID 41346687, 2025). "In fact, low albumin and hemoglobin levels are associated with poor survival of cancer patients." (PMID 40282930, 2025). "However, prior studies have not established a clear association between nutritional supplementation and serum albumin response, even when administered in critically ill patients such as those with advanced cancer." (PMID 40103850, 2025). "Therefore, cancer patients with low albumin counts were linked to dietary deficiencies, inadequate anticancer responses, and reduced immunological responses." (PMID 40095849, 2025). "Components of the Child–Pugh score, such as ascites, elevated total bilirubin levels, and decreased albumin levels, could be caused by the cancer itself." (PMID 40052520, 2025). "The strongest associations were seen in women with bloating, where cancer patients had 5-fold higher odds of having raised platelets (OR 4.78, 95%CI 3.68–6.21, P < 0.001) and 6-fold higher odds of having a low albumin (OR 6.23, 95%CI 4.51–8.62, p < 0.001) than controls." (PMID 39799273, 2025). "Rapidly growing and nutrient-deficient cancer cells readily absorb and metabolize ALB." (PMID 40601671, 2025). "This may be due to PNI, which consists of serum albumin and lymphocyte counts, is associated with the prognosis of various types of cancer." (PMID 39673205, 2025).
cancer (continued). "A meta-analysis of 18 BCa studies demonstrated that preoperative low albumin was significantly associated with inferior overall survival (OS) (HR = 1.88), cancer-specific survival (CSS) (HR = 1.69), 30-day postoperative complications (HR = 1.55), and 90-day mortality (HR = 2.87)." (PMID 40357040, 2025). "Decreased ALB levels are often linked with poor survival in patients with cancer." (PMID 40573274, 2025). "Albumin is a parameter that is often associated with cancer cachexia." (PMID 40786260, 2025). "Serum albumin is a frequently used nutritional status biomarker where nutritional deficiency impairs immune system, reduces the effectiveness of treatment, and increases the risk of unfavorable outcomes in cancer patients." (PMID 40416620, 2025). "Notably, high values of Age, HE4, and CA125 (shown in red) tend to push predictions toward the “Cancer” class, while higher values of ALB, LYM, RBC, and TBIL are generally associated with a decreased cancer probability." (PMID 40943960, 2025). "Furthermore, we find that supplementing with additives that contain necessary metals and any of the albumin-associated lipid classes can obviate the FBS requirement for cancer cell proliferation." (PMID 40930249, 2025). "Similarly, the ability of low albumin to predict cancer risk was similar across the three ethnic groups studied." (PMID 40941010, 2025). "Decreased serum albumin levels not only impair immune function but may also promote pro-inflammatory factors associated with cancer progression, increasing cancer risk." (PMID 40134599, 2025). "Additionally, numerous studies have demonstrated that pretreatment serum albumin is a significant prognostic marker for tumors, with low serum albumin levels being strongly associated with poor outcomes in cancer patients." (PMID 40741001, 2025). "To determine whether selective albumin-associated lipid consumption is specific to H1299 NucRFP cells or represents a broader phenotype of proliferating cancer cells, we profiled media lipids during growth across multiple cell lines." (PMID 40027810, 2025). "Additionally, cancer cachexia is associated with decreases in serum albumin, triglycerides (TG), cholesterol, high-density lipoprotein (HDL), and low-density lipoprotein (LDL) and increases in pro-inflammatory cytokines such as IL-6, IL-1β, and TNF-α." (PMID 40469669, 2025). "Infiltration of carcinoma cells might be easier in the state of lower albumin, and it may cause poor prognosis." (PMID 41008815, 2025). "Regarding the second stage of formation and evolution of NPPC structures, kinetic models in cancer nanomedicine were used to interpret association and dissociation of plasma proteins like human serum albumin (HSA), HDL over NP, it highlights the possible role of NPs size in corona formation." (PMID 40836967, 2024). "Furthermore, cancer treatments like chemotherapy and surgery can cause weight fluctuations and changes in serum albumin levels, further complicating GNRI interpretation." (PMID 39807216, 2024). "Association between serum albumin levels and cancer mortality in rare cancer types." (PMID 38500655, 2024). "In the present study, the authors found that the p-SOFA score was significantly higher in non-survivors than in survivors (p<0.001), and higher p-SOFA score and low albumin level were independently associated with increased death risk of cancer-related septic children." (PMID 38797509, 2024). "And serum albumin and cancer history might have interaction effects with all-cause mortality (p for interaction < 0.05)." (PMID 39026682, 2024). "Association between serum albumin levels and cancer mortality in different subgroups." (PMID 38500655, 2024). "Low albumin levels are additionally linked to an insufficient organismal anti-cancer response." (PMID 39013971, 2024).
cancer (continued). "Evidence from cohort studies suggests that adherence to physical activity guidelines is significantly associated with all-cause mortality (HR: 0.49; 95% CI: 0.38–0.63), malignancy mortality (HR: 0.30; 95% CI: 0.17–0.52), and albumin-to-creatinine ratio (OR: -0.27; 95% CI: -0.39 to -0.15)." (PMID 38172696, 2024). "Furthermore, reduced body mass index (BMI) and serum albumin (ALB), which mirror nutritional status, have also exhibited associations with adverse therapeutic outcomes across diverse types of cancers." (PMID 38741082, 2024). "However, an increase of ALB degradation is also a major cause of hypoproteinemia in cancer patients." (PMID 38915379, 2024). "Therefore, in cachexia-affected cancer patients, elevated serum albumin levels have been linked to lower 1-year death rates." (PMID 39768966, 2024). "Serum albumin was also utilized for nanoparticle formation in the form of drug-containing albumin-based nanoparticles, which are engineered for diagnostic and therapeutic purposes, including cancer treatment, due to their biocompatibility and ability to carry therapeutic agents." (PMID 39458651, 2024). "Various nutritional indicators have been studied in relation to AC tolerance due to S-1 in several types of cancers, including body weight loss, albumin-bilirubin score, geriatric nutritional risk index, prognostic nutritional index, and neutrophil-to-lymphocyte ratio." (PMID 38473284, 2024). "On the one hand, the majority of malignant tumors cause a transcriptional program to attract leukocytes, produce pro-oncogenic chemokines and cytokines, stimulate angiogenesis, and decrease albumin synthesis in the liver, which results in an intrinsic inflammatory response." (PMID 38360582, 2024). "Following adjustment for confounders, decreased albumin levels were associated with an elevated risk of cancer mortality across all groups [all cancers, HR (95%CI) = 2.03(1.73, 2.37); well survived cancers, HR (95%CI) = 1.78(1.38, 2.32); and poorly survived cancers, HR (95%CI) = 1.99(1.64, 2.42)]." (PMID 38500655, 2024). "Similarly, there is consensus in the literature regarding the poor prognosis associated with low albumin concentrations in cancer patients, reflecting the nutritional status of patients." (PMID 39400724, 2024). "Additionally, low levels of ALB or high levels of GLOB in many types of cancer are often associated with high mortality and recurrence rates." (PMID 39512347, 2024). "Serum albumin is a nutritional parameter commonly associated with cancer cachexia." (PMID 39590113, 2024). "Conversely, our data indicate that serum albumin levels should be considered not only as measure of oncotic pressure or epiphenomenon of underlying disease but also as a variable indicating a risk for vascular disease and cancer." (PMID 39010980, 2024). "Association between serum albumin levels and cancer mortality in specific cancer types." (PMID 38500655, 2024). "Similarly, our study showed that higher CRP/Albumin ratio was independently associated with higher cancer related mortality." (PMID 38803531, 2024). "The progressive cancer cells with chronic wasting biology could consume an amount of albumin, and a lower level of albumin implies a more advanced stage of disease, which was linked to a worse prognosis." (PMID 39064013, 2024). "Prealbumin deficiency was more common than albumin deficiency before and after cancer treatment." (PMID 39619813, 2024). "Albumin is also linked to immunological response and nutritional status in cancer patients." (PMID 38384810, 2024). "The Glasgow Prognostic Score (GPS) and modified GPS (mGPS) are validated risk calculators based on CRP and albumin levels, demonstrated to predict survival in cancer patients, including gastric, lung and renal cancer and for mGPS even in cancer patients independent of tumour site." (PMID 39691271, 2024). "Association between serum albumin levels and cancer mortality." (PMID 38500655, 2024).
cancer (continued). "Furthermore, individuals with history of cardiovascular disease or cancer or acute systemic inflammation -conditions typically associated with decreased serum albumin levels-were also excluded from the study." (PMID 39010980, 2024). "In addition to liver function, albumin is also one of the indicators of nutritional status and has been proven to be associated with the prognosis of various malignant tumours." (PMID 37522199, 2024). "Notably, low pretreatment serum albumin levels in cancer patients are associated with poor survival, and low serum albumin levels are associated with poor response to various chemotherapies and tyrosine kinase inhibitors (TKIs)." (PMID 38730986, 2024). "Additionally, cancer can cause cachexia, wasting, and reduced food intake, leading to insufficient nutrient intake and decreased albumin levels." (PMID 39687887, 2024). "Albumin is also responsible for transporting vital nutrients, including vitamins and minerals, throughout the body, which is crucial for maintaining a robust immune system and minimizing cancer risk." (PMID 37987317, 2023). "Due to the high expression of ALB (20%) and APOB’s ability to facilitate VLDL secretion (which consumes large amounts of energy), mutation of ALB or APOB may be inactivated to divert energy into cancer-relevant metabolic pathways." (PMID 36881382, 2023). "As a significant source of amino acids, albumin contributes to essential protein synthesis required for healthy cell growth and division; deficiencies in this synthesis have been correlated with an elevated cancer risk." (PMID 37987317, 2023). "By evaluating body composition by anthropometric means and systemic inflammation biomarkers (e.g., albumin, white blood cell, neutrophile, lymphocyte, and platelet counts), the risk of cancer cachexia and need for nutritional intervention have been established." (PMID 37571328, 2023). "The reduction in albumin levels in EAC-induced mice could be due to the presence of hepatic damage caused by cancer cells invasion, which manifested as abridged biosynthetic abilities." (PMID 38098043, 2023). "Moreover, albumin decrease has been shown to be associated with rapid clearance of pembrolizumab in advanced cancer." (PMID 36839241, 2023). "In addition to reflecting the nutritional status of the human body, ALB has been proposed to be an endogenous antioxidant that can reduce cancer risk by exerting anti-cancer properties." (PMID 36980604, 2023). "Hemoglobin, LDH, CRP, and albumin levels could be used as predictive factors for cancer patients with associated type two diabetes, highlighting the importance and impact of metabolic and inflammatory disorders encountered in these chronic diseases." (PMID 37627906, 2023). "A multifunctional cancer-associated site specific delivery system and two-modal imaging-assisted co-loaded therapy for tumor have both been created using nanotheranostics based on albumin." (PMID 36866455, 2023). "Although the underlying cause of low albumin levels in cancer patients remains unknown, it has been demonstrated that high levels of IL-6 produced by cancer cells inhibit the production of albumin." (PMID 37509622, 2023). "Serum albumin and other clinical and laboratory variables might be associated with early post-treatment deaths in patients with cancer." (PMID 37674155, 2023). "The lower albumin levels were independently associated with the presence of cancer, while the levels of bilirubin, alanine transaminase, and aspartate transaminase were similar in patients with or without cancer in the pivotal Glasgow Inflammation Outcome Study." (PMID 36533070, 2022). "The definite algorithm, called the aMAP score, selected older age, male sex, albumin–bilirubin and low platelet count as cancer predictors and was able to identify a high-risk group that accounted for ∼18% of the overall population with an HCC incidence of 19.9% at 5 years." (PMID 34977518, 2022).